SOST (sclerostin)
Diseases named in the same sentence as SOST in open-access papers (continued):
Sharing a sentence is not in itself a finding about the gene and the disease.
osteosarcoma (continued). "We investigated the effect of sclerostin, a canonical Wnt pathway inhibitor and osteogenesis suppressor, on osteosarcoma." (PMID 34885123, 2021). "Next, human sclerostin was administered to nude mice that were subcutaneously transplanted with human osteosarcoma cell line 143B." (PMID 34885123, 2021). "Sclerostin inhibited the proliferation and migration of osteosarcoma cell lines, suppressed tumor growth, and promoted the survival of osteosarcoma-implanted mice." (PMID 34885123, 2021). "When tested in the alamarBlue assay, the addition of sclerostin to the culture medium of the human osteosarcoma cell line 143B significantly inhibited the growth of the cell line (p = 0.040)." (PMID 34885123, 2021). "In a mouse model that was subcutaneously transplanted with a human osteosarcoma cell line, sclerostin was found to inhibit osteosarcoma growth and prolong overall survival." (PMID 34885123, 2021). "Next, to analyze the effect of sclerostin on the migration ability of the mouse osteosarcoma cell line, we performed a migration assay and found that sclerostin significantly inhibited the migration of LM8 (p = 0.000002)." (PMID 34885123, 2021). "To more precisely characterize the dynamics of mechanically stimulated sclerostin protein loss in osteocytes, we examined two sclerostin expressing cell lines: Ocy454 osteocytes and UMR106 osteosarcoma cells." (PMID 33779549, 2021). "The results suggest that sclerostin inhibits not only the proliferation but also the migration of mouse osteosarcoma cells." (PMID 34885123, 2021). "As a well-known negative regulator of bone formation, sclerostin inhibits the proliferation and differentiation of cementoblasts and osteoprogenitor cells including osteosarcoma cells (Zou, Zhang & Li, 2017) and human mesenchymal stem cells." (PMID 30356963, 2018). "On the other hand, sclerostin was found to be expressed and upregulated in osteosarcoma." (PMID 37755271, 2023). "Furthermore, sclerostin is expressed by tumor cells in most high-grade osteosarcomas and pariosteal osteosarcomas." (PMID 34830568, 2021). "Sclerostin is expressed by osteocytes in mineralized bone and by mineralizing chondrocytes in articular cartilage and the growth plate in most primary bone tumors, such as osteoma, osteoid osteoma, osteoblastoma, and osteosarcoma." (PMID 34830568, 2021). "This study aims to examine the antitumor effect of sclerostin on osteosarcoma." (PMID 34885123, 2021). "Furthermore, we showed that sclerostin inhibited the growth of the tumor and prolonged the survival time in the mouse model of osteosarcoma." (PMID 34885123, 2021). "Furthermore, sclerostin was expressed by tumor cells in most high-grade osteosarcomas and parosteal osteosarcomas." (PMID 34830568, 2021). "In addition, a scratch assay was performed to clarify the effects of sclerostin on the proliferation and migration of mouse osteosarcoma cell lines." (PMID 34885123, 2021). "An assessment on the effects of sclerostin in combination with existing antitumor drugs may provide important insights for novel treatment strategies of osteosarcoma and warrants further investigation." (PMID 34885123, 2021). "Likewise, inhibition of lysosomal activity with bafilomycin A1 or leupeptin prevented FSS-induced sclerostin degradation in UMR106 osteosarcoma cells." (PMID 33779549, 2021). "Sclerostin suppressed the proliferative capacity and migratory ability of osteosarcoma cells." (PMID 34885123, 2021). "We aimed to investigate the antitumor effect of sclerostin against osteosarcoma." (PMID 34885123, 2021). "Thus, sclerostin as a novel therapy is intended to be used only for osteosarcoma, which is defined by its bone formation." (PMID 34885123, 2021). "We examined whether the inhibitory effects of sclerostin on the proliferation and migration of mouse cell lines can also be observed in human osteosarcoma cell lines." (PMID 34885123, 2021).
osteosarcoma (continued). "A response of osteocytes to IL-11 has not been reported previously, but IL-11 stimulates STAT3 phosphorylation in primary calvarial osteoblasts, and we have observed downregulation of sclerostin by IL-11 in an osteosarcoma-derived cell line (UMR106-01, Patricia W.M. Ho, unpublished data)." (PMID 32458800, 2020). "It has been demonstrated that demethylation of the SOST promoter by 5-aza-2′-deoxycytidine (AzadC) induces a strong increase in SOST expression in MG63 osteosarcoma cell line, presumably by facilitating the binding of transcription factors to the proximal promoter." (PMID 30729116, 2019). "Additionally, SOST levels are elevated by hypoxia in human Saos-2 osteogenic sarcoma cells." (PMID 37198221, 2023). "We hypothesized that sclerostin would prevent the growth and metastasis of osteosarcoma, which is characterized by abnormal bone formation by inhibiting the canonical Wnt pathway in osteosarcoma cells." (PMID 34885123, 2021). "Second, sclerostin inhibits osteogenesis, which is a common definition for all osteosarcomas; thus, it may be effective for many patients, even in those with highly diverse osteosarcomas." (PMID 34885123, 2021). "Similarly, PTH treatment was showed to reduce serum sclerostin levels in postmenopausal women that may also lead to osteosarcoma." (PMID 32664215, 2020). "When sclerostin was added to the culture medium of the mouse osteosarcoma cell line LM8, sclerostin significantly inhibited the growth of LM8 (p < 0.001, p = 0.0000018)." (PMID 34885123, 2021). "Consistent with our previous work, we observed the mechano-activated increase in CaMKII phosphorylation and decrease in sclerostin protein abundance in both Ocy454 osteocytes and UMR106 osteosarcoma cells within 5 min of the acute application of FSS." (PMID 33779549, 2021). "Another study showed reduced SOST expression and increased Wnt/β‐catenin signaling in the rat UMR106.01 osteosarcoma and mouse MLO‐A5 osteoblastic cell lines, consistent with a pro‐anabolic effect of hypoxia, although effects on in vitro mineralization were not reported." (PMID 37929653, 2023). "The precise role of sclerostin is not clear, and evidence regarding the role of Wnt-signaling pathway in osteosarcoma is contradictory." (PMID 34830568, 2021). "In osteoma, osteoid osteoma, osteoblastoma, and osteosarcoma, osteocytes and chondrocytes from both articular cartilage and growth plate express sclerostin, while osteoblasts in osteoid osteomas and osteoblastomas, did not express sclerostin." (PMID 35160258, 2022). "Sporadic reports have noted SOST expression by several nonosteocytic cells in mammals—by hypertrophic and osteoarthritic chondrocytes, osteoblast-like osteosarcoma cells, and even in normal osteoblasts, albeit at low levels; however, these observations were not linked to bone-modeling regulation." (PMID 30707688, 2019). "Most high-grade osteosarcomas and parosteal osteosarcomas express sclerostin after the binding of the Runx2 to the SOST gene upstream promoter region, although sclerostin’s exact role is not known." (PMID 35160258, 2022).
calcification (19 papers, 2013 to 2025). Process by which organic tissue becomes hardened by the physiologic deposit of calcium salts. "Among these factors, evidence had shown that sclerostin played an important role and increased expression of sclerostin was associated with vascular calcification." (PMID 32075016, 2020). "Thus, sclerostin expression has been found in atherosclerotic plaques and has been linked to vascular calcification in menopausal women, diabetic patients, and in those with abnormalities in the thickness of the arterial intima-media layers." (PMID 36498053, 2022). "The association of sclerostin with mortality may reflect its role in vascular calcification." (PMID 30314461, 2018). "Conversely, in another mouse model of vascular calcification induced by warfarin, anti-sclerostin treatment increased aortic and vascular calcification, suggesting a protective role for sclerostin against vascular calcification." (PMID 38474734, 2024). "The fact that sclerostin is the sole independent factor related to vascular calcification in a logistic regression analysis, being displaced only by age, is a striking result." (PMID 36895513, 2023). "Warfarin-exposed rats developed vascular calcifications in a time-dependent manner which went along with a progressive increase in serum sclerostin levels." (PMID 31330917, 2019). "In fact, Sclerostin is currently regarded as a promising new player in CKD-MBD, possibly implicated with the pathomechanisms of vascular calcification and cardiovascular mortality." (PMID 28558021, 2017). "Importantly, sclerostin levels were not only related to vascular calcification in our study, but also to a possible consequence of vascular calcification, namely brain atrophy." (PMID 36895513, 2023). "On the other hand, sclerostin is a reliable and early biomarker of vascular calcification." (PMID 36517533, 2022). "Considering the strongly indicative role of vascular calcification in cardiovascular events, serum sclerostin may add prognostic power for MACCEs and its component because of its role in regulating vascular calcification." (PMID 31677125, 2020). "This may also explain the gradual increase in serum sclerostin levels of animals with progressing ectopic vascular calcification, as observed in our present study." (PMID 31330917, 2019). "The upregulation of SOST effectively downregulates the expression of matrix metalloproteinase 9 (MMP9) and OPG, which are involved in the activation of arterial calcification in Ang II mice." (PMID 40563496, 2025). "The upregulation of SOST effectively downregulates the expression of osteopontin (OPN), which facilitates inflammation and activates arterial calcification in Ang II mice, as well as OPG, which is involved in the activation of arterial calcification in Ang II mice." (PMID 40563496, 2025).
Stroke (19 papers, 2016 to 2025). Sudden impairment of blood flow to a part of the brain due to occlusion or rupture of an artery to the brain. "Another MR study using sclerostin gene expression in arterial and heart tissue as the exposure suggested little evidence of a causal effect of sclerostin expression on risk of MI or stroke." (PMID 37096546, 2023). "The inhibition of sclerostin may promote vascular calcification, a known risk factor for MI, stroke, and other cardiovascular events." (PMID 39767786, 2024). "However, evidence suggests that sclerostin inhibition may adversely affect vascular calcification, potentially increasing the risk of myocardial infarction (MI) and stroke." (PMID 39767786, 2024). "Interestingly, within the first few days following an acute stroke event, patients already display elevated serum concentrations of bone turnover markers including osteoprotegerin, sclerostin, dickkopf-related protein 1 and osteopontin, suggesting direct correlation of stroke and bone loss." (PMID 32668736, 2020). "Studies are also present showing that high sclerostin levels was found in patients with stroke compared to health controls." (PMID 39078512, 2024). "In postmenopausal women immobilized after a stroke, sclerostin correlated negatively with bone formation markers and positively with resorption markers." (PMID 31164134, 2019). "In patients with stroke a gender difference in serum levels of sclerostin was observed, meriting further investigation." (PMID 30496210, 2018). "Serum levels of OPG, OPN, DKK1, and sclerostin were much higher in stroke patients compared to controls." (PMID 30496210, 2018). "We found clearly increased serum levels of osteoprotegerin, sclerostin, dickkopf-1 and osteopontin in patients with stroke compared with healthy controls." (PMID 30496210, 2018). "Serum levels of sclerostin were significantly higher in the stroke group." (PMID 38644839, 2024). "Thus, the literature suggests a positive association between high sclerostin serum levels and the development of CVD in patients with incident stroke." (PMID 36498053, 2022). "Immobilization occurring with severe illness, which has been described to increase sclerostin expression due to mechanical unloading (e.g., after stroke), may be an alternative explanation for the elevated serum sclerostin levels in AKI." (PMID 34822428, 2021). "We did find a correlation between plasma creatinine, eGFR and sclerostin in stroke patients." (PMID 30496210, 2018). "Sclerostin in stroke patients was found to correlate with waist circumference." (PMID 30496210, 2018). "Men with stroke exhibited higher levels of sclerostin compared to women." (PMID 30496210, 2018). "Similarly, postmenopausal women who became immobile as a result of stroke had significantly higher serum sclerostin concentrations than controls; this was accompanied by a decreased bone stiffness index determined by quantitative ultrasound." (PMID 27278385, 2016). "However, concerns have been raised about the possibility of serious adverse cardiovascular events following sclerostin inhibition, and anti-sclerostin antibodies are generally contraindicated in case of a history of myocardial infarction or stroke." (PMID 38591777, 2024). "Currently, the existing data so far backs the notion of limiting the prescription guidelines outlined in the data sheet, which suggests that patients with a high risk of cardiovascular disease and stroke should not be eligible for treatment with anti-sclerostin antibody." (PMID 37919715, 2023). "In the present study we investigated whether the BTMs sclerostin, OPG, OPN, OC and DKK-1 could be useful as biomarkers to predict increased risk of new fractures, new cardiovascular events or mortality in a cohort of elderly patients with fractures, stroke and volunteers." (PMID 38644839, 2024). "One study found clearly increased serum levels of sclerostin and DKK-1 (also of OPG and OPN) in patients with stroke compared with volunteers." (PMID 38644839, 2024).
Stroke (continued). "Romosozumab, a monoclonal antibody to sclerostin, is a new osteoanabolic drug that increases bone formation and decreases bone resorption, which is recommended as preliminary treatment in patients with a very high fracture risk without a history of stroke or myocardial infarction." (PMID 37635980, 2023). "Serum levels of sclerostin, DKK1, OPG and OPN were significantly higher in patients with stroke compared with controls." (PMID 30496210, 2018). "However, whereas the cis instrument suggested a causal effect of sclerostin lowering on CAC and MI, there was no equivalent effect on AAC or stroke." (PMID 37096546, 2023). "However, in our study, sclerostin levels did not significantly impact the stroke rate." (PMID 33800939, 2021). "A correlation was seen between renal function parameters (plasma creatinine and eGFR) and two of the biomarkers (sclerostin and OCN) in patients with stroke, but no such correlation was observed in the control group." (PMID 30496210, 2018).
osteogenesis imperfecta (18 papers, 2019 to 2025). Osteogenesis imperfecta (OI) comprises a heterogeneous group of genetic disorders characterized by increased bone fragility, low bone mass, and susceptibility to bone fractures with variable severity. "The profile of serum sclerostin levels in patients with osteogenesis imperfecta (OI), X-linked hypophosphatemia (XLH), and Paget's disease of bone (PDB) was obtained to determine their association with bone turnover marker." (PMID 36124027, 2022). "Pharmacologically,GalNAc-Apc001 exhibited superior therapeutic efficacy by mitigatingthe suppressive effects of sclerostin on Wnt signaling, upregulatingbone formation markers, and enhancing bone mass in a Col1a2+/G610C osteogenesis imperfecta mousemodel." (PMID 41450662, 2025). "Remarkably, the long-lasting sclerostin aptamer for osteogenesis imperfecta (OI) was granted Rare Pediatric Disease Designation (RPD-2022-667) and Orphan Drug Designation (DRU-2022-9087) by the US Food and Drug Administration (FDA) in 2022." (PMID 38074899, 2023). "Sclerostin antibody (SclAb) therapy has been suggested as a novel therapeutic approach toward addressing the fragility phenotypic of osteogenesis imperfecta (OI)." (PMID 32803109, 2020). "Clinical trials of BPS804, a fully humanized sclerostin neutralizing antibody, in hypophosphatasia and osteogenesis imperfecta are also underway." (PMID 31698687, 2019). "AGA-2115 (Angitia Biopharmaceuticals) is also a humanized bispecific antibody that targets sclerostin and DKK1 which is in Phase 1 clinical development for the treatment of osteogenesis imperfecta." (PMID 40394415, 2025). "Anti-sclerostin antibodies were able to improve bone strength and microarchitecture, and to reduce axial and long bone fractures in animal models of osteogenesis imperfecta (OI)." (PMID 33114755, 2020). "Although this dose of romosozumab (30 mg/kg, twice monthly) has not been evaluated in humans, another sclerostin antibody was administered at 20 mg/kg or 40 mg/kg monthly up to 6 months in patients with osteogenesis imperfecta and appeared to be safe in subjects with osteogenesis imperfecta." (PMID 40809811, 2025). "However, finding that the brittleness of A/J femurs was not improved following Scl-Ab treatment is consistent with the work of others which showed Brtl/+ mice (Type IV osteogenesis imperfecta (OI) model) treated with a sclerostin antibody failed to significantly improve tissue ductility." (PMID 30947279, 2019).